C17orf99 (chromosome 17 open reading frame 99)
Description:
Probable B cell-associated cytokine that plays a role in the regulation of humoral immune responses. Involved in lymphocyte B cell development and immunoglobulin/IgA production.
Synonyms: IL-40; IL40; GLPG464; UNQ464
Tractability: Antibody: UniProt places it where antibodies can reach, with high confidence; UniProt predicts a signal peptide or a membrane-spanning region; its Gene Ontology location is reachable by antibodies, with medium confidence.
Gene: Protein-coding gene on chromosome 17 (78,146,385 to 78,166,297, forward strand). Ensembl gene ENSG00000187997.
Subcellular location: Secreted
Gene Ontology:
Molecular function: transmembrane signaling receptor activity
Biological process: cell surface receptor signaling pathway; immune response; mature B cell differentiation involved in immune response; positive regulation of immunoglobulin production in mucosal tissue
Cellular component: extracellular region; external side of plasma membrane
Genetic constraint (gnomAD): Loss-of-function variants: 18 observed, 23.22 expected, observed/expected ratio (o/e) 0.78, 90% interval 0.54 to 1.15. The upper end of that interval is the gene's LOEUF score, 1.15, which puts it in group 5 of 6, group 1 being the genes least tolerant of losing a copy. Missense variants: 305 observed, 310.25 expected, observed/expected ratio (o/e) 0.98, 90% interval 0.89 to 1.08. Synonymous variants: 139 observed, 126.07 expected, observed/expected ratio (o/e) 1.1, 90% interval 0.96 to 1.27.
Homologues: Orthologues: chimpanzee C17H17orf99 (95% identical), macaque C16H17orf99 (87% identical), dog C17orf99 (52% identical), mouse 6030468B19Rik (46% identical), rat C10h17orf99 (46% identical). Paralogues in human: FCRL5 (18% identical), PECAM1 (18% identical), FCGR1A (15% identical), FCRL3 (15% identical), FCRL4 (15% identical), FCRLB (14% identical), FCGR2A (13% identical), FCGR2B (13% identical), FCGR3A (13% identical), FCGR3B (13% identical), FCGR2C (12% identical), FCRLA (12% identical), and 5 more.
Diseases named in the same sentence as C17orf99 in open-access papers:
C17orf99 is named in the same sentence as 31 diseases in open-access papers, as found by Europe PMC text mining. Sharing a sentence is not in itself a finding about the gene and the disease.
C17orf99 shares sentences with these, for which no sentence is quoted: rheumatoid arthritis (8 papers); autoimmune disease (6); Sepsis (4); systemic lupus erythematosus (4); ankylosing spondylitis (3); osteoarthritis (3); pneumonia (3); primary Sjögren’s syndrome (3); type 2 diabetes (3); B cell lymphoma (2); COVID-19 (2); diabetes (2); infection (2); infectious disease (2); lymphoma (2); ANCA-associated vasculitis (1); Arthritis (1); autoimmune hepatitis (1); Autoimmunity (1); cancer (1); cardiovascular diseases (1); coronary artery disease (1); Graves disease (1); heart disease (1); injury (1); membranous nephropathy (1); metabolic disease (1); Multiple Organ Failure (1); myasthenia gravis (1); non-lymphoma Hodgkin's (1).
A further 1 disease shares a sentence with C17orf99 in 1 paper.